DANCR (differentiation antagonizing non-protein coding RNA)
Diseases named in the same sentence as DANCR in open-access papers (continued):
Sharing a sentence is not in itself a finding about the gene and the disease.
breast tumor (2 papers, 2019 to 2021). "In addition, animal experiment also demonstrated that high level of DANCR had promoting roles on breast tumor growth and Ki67 activity." (PMID 30910842, 2019).
COVID-19 (2 papers, 2020 to 2022). A disease caused by infection with severe acute respiratory syndrome coronavirus 2. "Supporting active involvement in the inflammatory risks accompanying COVID-19, DANCR’s decline associated with decrease of the COVID-19-related cellular transcript ACE2 and with sex-related increases in coding transcripts potentiating acetylcholine signaling." (PMID 33163005, 2020). "The specific mechanism of action of lncRNA DANCR/NEAT1-miR-19a-3p/miR-335-5p-HIF1a/CCR7/TLR4 in COVID-19 patients’ needs to be further elucidated." (PMID 36204652, 2022). "The DANCR knockdown model as well supports the observed findings in COVID-19-related lung epithelial tissues, where DANCR emerges as an important inflammatory controller." (PMID 33163005, 2020). "Supporting a functional role of DANCR in COVID-19, we have further identified correlation of DANCR expression levels with those of the membrane-bound ACE2 protein in lung specimens of healthy donors." (PMID 33163005, 2020). "Although at this stage it is difficult to ascertain how these differences explain the sex disparity in the consequences of COVID-19, it highlights DANCR as a putative marker for ongoing research in this question." (PMID 33163005, 2020). "Thus, the non-coding regulators igniting and propagating COVID-19 may provide potential mechanistic explanations to the hazards incurred by at-risk populations, and our findings bring ncRNAs at large, and DANCR and NEAT1 in particular, to the realm of COVID-19 and its aftermath." (PMID 33163005, 2020). "LncRNAs can monitor cholinergic signaling in response to COVID-19; lncRNA DANCR and lncRNA NEAT1 affect nerve tissues through cholinergic mediators, and their upregulation may change the inflammatory state of neurons." (PMID 36204652, 2022). "We discovered the lung pathology-associated lncRNA DANCR and the nuclear paraspeckles forming neuroprotective lncRNA NEAT1 as potentially involved in the susceptibility to and consequences of COVID-19, in conjunction with acetylcholine and inflammation-regulating transcripts." (PMID 33163005, 2020). "Taken together, our findings may assist future management of COVID-19 patients, as they may exhibit diverse expression profiles of molecular regulators such as DANCR and NEAT1, in conjunction with previously depicted inflammatory mediators such as IL-1, IL-6, TNF, and more." (PMID 33163005, 2020). "Our current finding of DANCR’s decline in inflammation-prone lung tissue, in tandem with the accumulating evidence pertaining to DANCR’s role in inflammation and in infected cell cultures, led to our prediction that DANCR’s decline might play a role in COVID-19." (PMID 33163005, 2020). "Thus, DANCR and NEAT1 both appear to act as kernels to a network of genes involved in inflammation and diverse infections, at least in the context of COVID-19." (PMID 33163005, 2020).
multiple myeloma (2 papers, 2020 to 2023). "DANCR exhibits different biological functions in different tumor types: KLF12 mediates the promotive effect of DANCR in HCC, while KLF9 is the ultimate target of the cancer-inhibiting effect of DANCR in multiple myeloma." (PMID 36761967, 2023).
neuroblastoma (2 papers, 2020 to 2026). Neuroblastoma (NB) is the most common solid, extracranial childhood tumor. "Considering the tumorigenic effect of DANCR in neuroblastoma cells, we aimed to elucidate its underlying molecular mechanism and identify associated regulatory genes." (PMID 41602364, 2026). "All these outcomes underscore the essential regulatory role of DANCR in the proliferation, metastatic, and invasion capabilities of neuroblastoma cells." (PMID 41602364, 2026). "Pathway analysis revealed that DANCR is involved in the regulation of the actin cytoskeleton, which is a process integral to the migratory capacity of neuroblastoma cells." (PMID 41602364, 2026). "The total RNA of 64 neuroblastoma tissue samples was extracted for further validation of the relationships among miR-125a-5p, DANCR, and ABL2." (PMID 41602364, 2026). "To better elucidate the role of DANCR in neuroblastoma cells, we assessed its expression level in five neuroblastoma cell lines (SH-SY5Y, SK-N-AS, SK-N-SH, SK-N-Be2, and IMR-32) using qRT-PCR." (PMID 41602364, 2026). "Overall, we concluded that the DANCR/miR-125a-5p/ABL2/SSH1/cofilin signaling pathway regulated the metastatic ability of neuroblastoma." (PMID 41602364, 2026). "In the neuroblastoma cell lines SK-N-Be2 and SK-N-AS, the pcDNA3.1(+)-DANCR vector significantly induced DANCR overexpression, whereas the siRNA constructs siDANCR-2 and siDANCR-3 effectively inhibited its expression, measured by qRT-PCR." (PMID 41602364, 2026). "In conclusion, the results of the present study revealed that DANCR functions as a ceRNA to aggravate neuroblastoma metastasis by targeting the miR-125a-5p/ABL2/cofilin axis." (PMID 41602364, 2026). "In vitro functional experiments demonstrated that DANCR promotes the proliferation, migration and invasion of neuroblastoma cells." (PMID 41602364, 2026). "To elucidate the influence of DANCR on the biological behavior of neuroblastoma cells, we generated the recombinant plasmid pcDNA3.1(+)-DANCR for overexpression and siDANCR for knockdown." (PMID 41602364, 2026). "In our studies, we found that DANCR promoted the metastatic ability of neuroblastoma cells by targeting its downstream gene ABL2." (PMID 41602364, 2026). "We verified that DANCR overexpression in neuroblastoma cells significantly enhances the interaction of ABL2 with cortactin, which also affects SSH1-cofilin activity and stabilizes F-actin networks." (PMID 41602364, 2026). "Our study highlights the role of DANCR in neuroblastoma metastasis, emphasizes its regulatory relationship with miR-125a-5p and ABL2, and provides a new perspective for neuroblastoma therapy." (PMID 41602364, 2026). "Additionally, to investigate the effect of DANCR on neuroblastoma progression, we validated the expression of DANCR at the transcript level in 139 neuroblastoma tissues using qRT-PCR." (PMID 41602364, 2026). "In general, DANCR facilitates the malignant phenotype in neuroblastoma." (PMID 41602364, 2026). "Crucially, our study links DANCR to ABL2-driven cytoskeletal dynamics in neuroblastoma." (PMID 41602364, 2026). "Collectively, these results imply that DANCR may have a critical influence on neuroblastoma carcinogenesis." (PMID 41602364, 2026). "We further evaluated the functional effects of DANCR on neuroblastoma cells in vitro." (PMID 41602364, 2026). "Therefore, we investigated the effect of DANCR on the cytoskeleton in neuroblastoma cell lines by immunofluorescence." (PMID 41602364, 2026). "To date, related studies on DANCR and neuroblastoma are rare." (PMID 41602364, 2026). "Moreover, regulating the expression of miR-125a-5p significantly reversed the function of DANCR in neuroblastoma." (PMID 41602364, 2026). "In summary, our findings delineate the DANCR/miR-125a-5p/ABL2/cofilin axis as a critical regulator of cytoskeletal dynamics in neuroblastoma metastasis, offering novel insights for the diagnosis and therapeutic targeting of high-risk neuroblastoma." (PMID 41602364, 2026).
neuroblastoma (continued). "Therefore, we hypothesized that DANCR may play a role in the cytoskeletal regulatory network, which we verified via coimmunoprecipitation (co-IP) and western blotting in neuroblastoma cells." (PMID 41602364, 2026). "Furthermore, according to the Kaplan-Meier survival analysis conducted with the database (GSE16476, GSE62564, TARGET), neuroblastoma patients with higher expression of DANCR featured a significantly poorer overall survival rate than patients with lower DANCR expression (P < 0.001)." (PMID 41602364, 2026). "Cell growth curve analysis revealed that, compared with the control, DANCR overexpression significantly increased the proliferative ability of SK-N-Be2 and SK-N-AS cells, whereas DANCR knockdown substantially diminished the viability of these neuroblastoma cells." (PMID 41602364, 2026). "Indeed, overexpression of DANCR markedly enhanced the formation of lamellipodia, while suppression of DANCR expression substantially depressed lamellipodia formation, suggesting that DANCR could modulate the mobility of neuroblastoma cells by targeting the cytoskeleton." (PMID 41602364, 2026). "Together, we concluded that DANCR promoted ABL2-mediated proliferation and metastasis by acting as a ceRNA by decoying miR-125a-5p in neuroblastoma." (PMID 41602364, 2026). "Therefore, our study suggests that DANCR is an oncogenic lncRNA that promotes neuroblastoma progression via the DANCR/miR-125a-5p/ABL2 axis, which may serve as a novel prognostic biomarker and therapeutic target for neuroblastoma." (PMID 41602364, 2026).
osteoarthritis (2 papers, 2023 to 2024). A noninflammatory degenerative joint disease occurring chiefly in older persons, characterized by degeneration of the articular cartilage, hypertrophy of bone at the margins and changes in the synovial membrane. "While DANCR has been reported to exhibit aberrant expression in conditions such as novel coronavirus pneumonia infection, and osteoarthritis, it has also been identified as a regulator of oxidative stress in sarcopenia." (PMID 38609873, 2024). "Inflammation exacerbates DN progression, and DANCR dysregulation has been reported in osteoarthritis, colitis, and severe acute respiratory syndrome coronavirus infection." (PMID 38609873, 2024). "In addition, lncRNA DANCR was elevated in osteoarthritis patients and was validated as a useful biomarker and treatment target for osteoarthritis." (PMID 37779916, 2023). "Moreover, lncRNA DANCR influenced chondrocyte proliferation and apoptosis through regulation of miR-216a-5p, JAK2 and STAT3 pathways in osteoarthritis." (PMID 37779916, 2023).
renal cell carcinoma (2 papers, 2019 to 2022). "All conducted studies have indicated up-regulation of DANCR in cancer tissues/cell lines except for a single study in renal cell carcinoma." (PMID 35590326, 2022).
Stroke (2 papers, 2018 to 2020). Sudden impairment of blood flow to a part of the brain due to occlusion or rupture of an artery to the brain. "Among the top 18 miRNAs of which the predictive binding scores were higher than 0.9, miR-335-5p and miR-1972 stroke our sight because DANCR and ROCK1 shared the similar miRNA response elements (MREs) for miR-335-5p and miR-1972 (predicted by DIANA-LncBase and TargetScan)." (PMID 29753317, 2018). "Thus, DANCR and miR-33a-5p may be a therapeutic target for the treatment of stroke." (PMID 31986122, 2020).
acute myeloid leukemia (1 paper, 2020). Acute myeloid leukemia (AML) is a group of neoplasms arising from precursor cells committed to the myeloid cell-line differentiation. "Of interest here is the finding that DANCR plays a role in Acute Myeloid Leukemia (AML)." (PMID 33134177, 2020).
colitis (1 paper, 2025). Inflammation of the colon. "It is noteworthy that research established that silencing DANCR could diminish the expression of inflammatory factors in rats with colitis, while overexpression of DANCR could augment inflammation following spinal cord injury, indicating a pro-inflammatory role for DANCR in disease." (PMID 41394397, 2025).
colorectal polyps (1 paper, 2020). "It was found that the level of serum DANCR in CRC, colorectal polyps and healthy control groups was 2.146 (1.363, 2.477), 1.399 (1.120, 1.671) and 1.287 (0.892, 1.686), respectively." (PMID 32159208, 2020).
colorectal tumor (1 paper, 2019). "Besides the ones that were reported to be dysregulated in colorectal tumor samples, such as CCAT1, H19, DANCR, ZFAS1, SNHG16, CYTOR, we have identified many others in this study including LUCRC." (PMID 32082365, 2019).
coronary artery disease (1 paper, 2022). "A recent study indicated that the lncRNA DANCR had aberrant expression levels in patients with coronary artery disease." (PMID 35235755, 2022). "It was also observed that DANCR was aberrantly expressed in peripheral blood mononuclear cells of patients with coronary artery disease and obstructive coronary atherosclerosis subjects." (PMID 35235755, 2022).
encephalitis (1 paper, 2025). An acute inflammatory process affecting the brain parenchyma. "The resultsindicated that in the encephalitis group, potassium channel-related gene KCNN3,cell development-related genes EMC8, DANCR, and ASPN, along with thetranscription factor ZNF296, were significantly upregulated." (PMID 40985687, 2025).
gestational diabetes mellitus (1 paper, 2020). "DANCR has been shown to act as a sponge for miR-33a-5p, which is upregulated in blood samples from patients with gestational diabetes mellitus (GDM)." (PMID 33628198, 2020).
glioblastoma (1 paper, 2022). The most malignant astrocytic tumor (WHO grade IV). "Literature-based functionality of these 14 DEPCGs showed that several of them were previously implicated in glioblastoma proliferation, invasiveness and treatment resistance, thereby explaining some of the pro-tumorigenic effects of DANCR." (PMID 36497269, 2022). "Interestingly, both DANCR and SNHG6 are targets of the miR-183/96/182 cluster in the DIANA-LncBase database, which suggests a possible DElncRNA/DEmiRNA interplay in glioblastoma." (PMID 36497269, 2022).
hyperlipidemia (1 paper, 2024). "DANCR may be a potent stimulator of hyperlipidemia and atherogenesis." (PMID 38968577, 2024).
influenza (1 paper, 2020). An acute viral infection of the respiratory tract, occurring in isolated cases, in epidemics, or in pandemics; it is caused by serologically different strains of viruses (influenzaviruses) designated A, B, and C, has a 3-day incubation period, and usually lasts for 3 to 10 days. "DANCR is notably active in lymphoid organs and T cell differentiation and presents massive increases following influenza vaccination." (PMID 33163005, 2020).
invasive breast carcinoma (1 paper, 2022). A carcinoma that infiltrates the breast parenchyma. "In patients with invasive breast carcinoma (IBC), higher levels of LIPG and signature genes of OXPHOS were found to be correlated with the presence of DANCR in the tumors (n = 1085)." (PMID 35954428, 2022).
ischemic stroke (1 paper, 2020). A stroke disorder caused by obstruction of blood flow to the brain, due to thrombotic (local blood clot formation) or embolic (due to a blood clot or other material traveling from another site) event. "In conclusion, we found that DANCR enhanced the survival and angiogenesis in OGD-treated BMECs through the miR-33a-5p/XBP1s axis, which provides a better understanding of the roles of DANCR and miR-33a-5p in ischemic stroke." (PMID 31986122, 2020). "Our findings indicate that DANCR overexpression and miR-33a-5p knockdown exhibit a protective effect in ischemic stroke." (PMID 31986122, 2020). "However, the role played by DANCR in ischemic stroke remains unclear." (PMID 31986122, 2020). "Additionally, DANCR promoted BMEC proliferation and angiogenesis through the regulation of miR-33a-5p/XBP1s in OGD-induced BMECs, which may be important for ischemic stroke therapies." (PMID 31986122, 2020).
lentivirus infection (1 paper, 2023). Virus diseases caused by the Lentivirus genus. "To further clarify the molecular function of DANCR in vitro, we constructed a THP-1 cell line that expressed excessive DANCR (hereinafter referred to as LV-DANCR cells) through lentivirus infection and puromycin screening." (PMID 37125193, 2023).
leukemia (1 paper, 2021). A malignant (clonal) hematologic disorder, involving hematopoietic stem cells and characterized by the presence of primitive or atypical myeloid or lymphoid cells in the bone marrow and the blood. "In two RNA‐seq datasets reported recently, DANCR was identified to be correlated strongly with features of leukemia stem cells, a subgroup of cells showing increased chemotherapy resistance." (PMID 33638615, 2021).
medulloblastoma (1 paper, 2021). A malignant, invasive embryonal neoplasm arising from the cerebellum. "To ascertain the role of these deregulated lncRNAs in the radiosensitivity of medulloblastoma cells, we knocked down RBM5-AS1, DANCR, and MALAT1 and overexpressed XIST in DAOY cells." (PMID 34225779, 2021).
pancreatic ductal adenocarcinoma (1 paper, 2020). An infiltrating adenocarcinoma that arises from the epithelial cells of the pancreas. "High DANCR expression was identified as an independent risk factor for poor OS and progression-free survival (PFS) of pancreatic ductal adenocarcinoma." (PMID 33123287, 2020). "DANCR could promote the proliferation and metastasis of pancreatic ductal adenocarcinoma cells." (PMID 33123287, 2020).
preeclampsia (1 paper, 2021). Preeclampsia is a hypertensive disorder of pregnancy that is characterized by new-onset hypertension with proteinuria presenting after 20 weeks of gestation, and depending on mild or severe forms may initially present with severe headache, visual disturbances, and hyperreflexia. "Studies have shown that lncRNA DANCR is down-regulated in placental tissues of patients with preeclampsia (PE)." (PMID 34652251, 2021).
pulmonary fibrosis (1 paper, 2020). Chronic progressive interstitial lung disorder characterized by the replacement of the lung tissue by connective tissue, leading to progressive dyspnea, respiratory failure, or right heart failure. "To investigate the regulatory mechanism by which DANCR promotes the EMT and pulmonary fibrosis, we sought to identify the differentially expressed genes between DANCR-overexpressing cells and control cells." (PMID 32010478, 2020). "In summary, our findings showed that ASP could downregulate the expression of DANCR, which in turn represses AUF1-mediated FOXO3 translation to suppress the EMT and pulmonary fibrosis." (PMID 32010478, 2020).
pulmonary tuberculosis (1 paper, 2023). A bacterial infection that affects the lungs and is caused by Mycobacterium tuberculosis. "To confirm this hypothesis, we collected the peripheral blood from 54 cases of pulmonary tuberculosis patients and 23 cases of healthy donors and detected the expression of DANCR in PBMCs using the qRT-PCR method." (PMID 37125193, 2023).
thyroid cancer (1 paper, 2019). "For another thing, in vitro and in vivo experiments needed to be conducted to further validate the biological function of DANCR in thyroid cancer." (PMID 30910839, 2019). "In other words, DANCR expression was negatively correlated with clinical stage/aggressive degree of thyroid cancers." (PMID 30910839, 2019). "DANCR expression was significantly decreased in III/IV stage thyroid cancer compared with I/II stage thyroid cancer and normal tissues in 76-pair samples." (PMID 30910839, 2019). "There are some potential mechanisms to explain the different expression of DANCR in thyroid cancer." (PMID 30910839, 2019).
tuberculosis (1 paper, 2023). A chronic, recurrent infection caused by the bacterium Mycobacterium tuberculosis. "The results showed that the expression levels of DANCR in tuberculosis patients were higher than in healthy controls (p = 0.0457), indicating a correlation between DANCR and M. tuberculosis infection." (PMID 37125193, 2023). "We found a higher expression of DANCR in tuberculosis patients compared to healthy controls, suggesting that DANCR might be associated with inflammation induced by M. tuberculosis infection." (PMID 37125193, 2023).